MAG (myelin associated glycoprotein)
Diseases named in the same sentence as MAG in open-access papers (continued):
Sharing a sentence is not in itself a finding about the gene and the disease.
neuropathy (continued). "When looking at the largest MN and UN CSA as measured by the UHF-US, significant between-group differences were seen for the studied nerves, suggesting substantial variations in nerve and fascicle enlargements in CIDP, d-CIDP and anti-MAG neuropathy compared to controls." (PMID 38409319, 2024). "Further, when focusing on the largest CSA measurements within the study, CIDP patients had a notably larger MN f-CSA (increase of 2.97 mm3, 95% CI (0.49, 5.46), p = 0.012) compared to those with anti-MAG neuropathy, indicating distinct patterns of nerve involvement between these conditions." (PMID 38409319, 2024). "BTKi did not seem to improve renal function (Case 1), while bortezomib‐based regimens demonstrated a beneficial activity on the hematological and organ response, even when used as second‐line therapy after chemoimmunotherapy (Case 3) and also with coexistence of anti‐MAG neuropathy (Case 2)." (PMID 38662353, 2024). "We present a prospective study aimed at comparing UHF-US alterations of nerves and fascicles in chronic inflammatory demyelinating polyradiculoneuropathy (CIDP), distal CIDP (d-CIDP) and anti-MAG neuropathy and their relationships with clinical and electrodiagnostic (EDX) features." (PMID 38409319, 2024). "Obinutuzumab has occasionally been used in anti-MAG antibody neuropathy." (PMID 35349079, 2022). "Anti-MAG neuropathy is a demyelinating neuropathy mediated by a monoclonal IgM antibody that binds to MAG protein and, different from CIDP, is not considered an inflammatory disease, and therefore, typical CIDP treatments are usually only transiently effective in these patients." (PMID 36672019, 2022). "The anti-HNK1 ELISA has high sensitivity (98%) and specificity (99%) in the diagnosis of anti-MAG neuropathy, and anti-HNK1 titers are correlated to the disease severity, suggesting that this test could be used as an outcome measure in clinical trials." (PMID 36672019, 2022). "The management of these patients is challenging as it is still unclear whether they are part of the anti-MAG neuropathy spectrum or represent a CIDP with false-positive anti-MAG." (PMID 36672019, 2022). "However, some cases of anti-MAG neuropathy can lack IgM monoclonal gammopathy with the disclosure of the IgM monoclonal protein after years of follow-up." (PMID 36672019, 2022). "The diagnosis of anti-MAG neuropathy is based on detecting the presence of anti-MAG antibodies." (PMID 36672019, 2022). "The anti-MAG antibodies are responsible for various neuropathies." (PMID 35624969, 2022). "A cut-off of >7000 BTU represents the best cut-off in recognizing anti-MAG neuropathy." (PMID 36672019, 2022). "Despite the two controlled trials enrolled only patients with IgM MGUS (being WM an exclusion criterion), patients with anti-MAG antibody neuropathy and WM display a similar response to rituximab, with a more persistent benefit in patients with short disease duration." (PMID 35349079, 2022). "Since about two-thirds of patients with this phenotype have IgM paraproteinemic neuropathy and often anti-MAG antibodies, EAN/PNS guidelines recommend testing an IgM protein and an anti-MAG antibody in patients with distal CIDP phenotype and repeating them if they are negative." (PMID 36672019, 2022). "Furthermore, the B-cell molecular status in anti-MAG neuropathy has given some understanding regarding its clonal origin." (PMID 34680279, 2021). "Patients with IgM MGUS and neuropathy can develop different clinical phenotypes; however, the most frequent one is a distal, symmetric, and demyelinating neuropathy associated with antibodies directed against MAG (myelin-associated glycoprotein)." (PMID 34680279, 2021). "Additionally, autoantibodies against myelin and MAG have been reported in several neuropathic syndromes, including anti-MAG neuropathy with distinct HNK-1 epitopes." (PMID 34827170, 2021).
neuropathy (continued). "Endoneurial immunoglobulin deposits were observed not only in anti-MAG antibody neuropathy but also in some cases of neuropathy with MGUS or hematologic malignancies and it is likely that the incidence of peripheral neuropathy is associated with endoneurial immunoglobulin deposits is underestimated." (PMID 33498362, 2021). "The neuropathy-associated with antibodies against myelin-associated glycoprotein, which is not a specific nodal/paranodal protein, showed paranodal abnormalities that mimicked iDSC before segmental demyelination." (PMID 31884566, 2020). "In our study, we identified that MAG might prevent acute and chronic neuropathies through ROS modulation." (PMID 31741707, 2019). "Unlike POEMS syndrome, neuropathy, when present, is mostly associated with IgM paraproteins, usually IgM kappa and many patients have antibodies targeting myelin-associated glycoprotein (MAG)." (PMID 30498913, 2019). "The diagnosis of Anti-MAG Neuropathy is through the detection of autoantibodies against MAG." (PMID 30941082, 2019). "This is the first study demonstrating that QoL, measured with SF36 questionnaire, was lower in patients with anti-MAG antibody neuropathy compared with the Italian general population, consistently with a previous study performed in French and English anti-MAG neuropathy population." (PMID 30306264, 2018). "In the past 25 years, numerous series have described anti-MAG neuropathy as a homogeneous entity." (PMID 26065001, 2015). "The selection of an effective immunosuppressive therapy for both diseases is very difficult, because MAG-related neuropathy is related to B cell immunity, whereas psoriasis is considered an autoimmune disease with T cells playing a key role in the pathogenesis." (PMID 23286283, 2013). "Although the efficacy of IVIg in IgM paraproteinemic neuropathies is not well established, the levels of IgM myelin-associated glycoprotein (MAG) and sulfoglucuronyl paragloboside (SGPG) antibodies are reduced in occasional patients treated with this therapy." (PMID 20514213, 2009). "Notably, monoclonal gammopathy may be associated with neuropathies mimicking CIDP, such as anti-MAG IgM neuropathy, POEMS syndrome, multiple myeloma, or AL amyloidosis." (PMID 39897200, 2025). "As a marker of axon-myelin stability, the decreased MAG expression in the CbCo, WB, and Hippo-CA1 regions indicated the disruption of the axonal function due to HIV-associated aging and could be a cause of neuropathy." (PMID 38399364, 2024). "Also, we describe the clinical, electrophysiological and laboratory findings of four patients with anti-MAG associated neuropathy without any detectable monoclonal gammopathy at the time of diagnosis." (PMID 30992531, 2019). "Anti-MAG titers could also be correlated with prognosis of the neuropathy." (PMID 30941082, 2019). "Altogether, our data suggest that patients with anti-MAG neuropathy based on ELISA testing may be divided in two subgroups, according to nerve conduction studies, nerve biopsy findings, immunofluorescence data, and titers of anti-MAG antibodies." (PMID 26065001, 2015). "Studies utilizing genetic (CNPase-, MAG-, and PLP-null mice) and naturally occurring neuropathy models suggest that myelinating glia also support axons independently from myelin." (PMID 36350884, 2022). "More recently, new causal-genes were identified in undiagnosed families, including PNKP in eight families with AOA4, MAG in one family with AOA and neuropathy, and DAB1 in three AD families with SCA37." (PMID 35326432, 2022). "For instance, anti-MAG antibodies have been documented in patients with IgM monoclonal gammopathy without clinical or electrophysiological evidence of neuropathy, even after prolonged follow-up." (PMID 40748018, 2025). "Unlike CIDP, anti-MAG antibody neuropathy typically presents as a slowly progressive, predominantly sensory, length-dependent polyneuropathy, often accompanied by tremor and ataxia [33▪▪]." (PMID 40748018, 2025).
neuropathy (continued). "Based on current evidence, there is no definitive correlation between anti-MAG antibody titers and the clinical severity or progression of neuropathy." (PMID 41031196, 2025). "On the other hand, in MAG antibody neuropathy, nerve enlargement is also seen in distal segments, without f-CSA increase." (PMID 38409319, 2024). "Anti-MAG neuropathy with atypical phenotype can be clinically indistinguishable from CIDP with M protein and positivity of anti-MAG (CIDP-MAG)." (PMID 36672019, 2022). "The present therapies for anti‐MAG neuropathy, using nonspecific immunosuppressives, act to reduce anti‐MAG antibodies, but due to a lack of selectivity lead to severe side effects." (PMID 33752265, 2021). "A few other cases of anti-MAG neuropathy in the absence of monoclonal gammopathy have been described, supporting our observations." (PMID 30992531, 2019). "In conclusion, we report four patients with anti-MAG neuropathy in the absence of IgM-monoclonal gammopathy." (PMID 30992531, 2019). "Though the score is not able to properly categorize CIDP-MAG in anti-MAG neuropathy and CIDP, it could predict the response to IVIg." (PMID 36672019, 2022). "Patients with MGUS and evidence of neuropathy should undergo an extended evaluation to rule out a hematologic disease, including a fat pad biopsy to look for amyloidosis and screening for anti-ganglioside and anti-MAG antibodies, as well as cryoglobulins." (PMID 32545521, 2020). "Anecdotal cases of neuropathy with anti-MAG antibodies lacking monoclonal gammopathy were reported." (PMID 30992531, 2019). "Very few cases of anti-MAG neuropathy lacking IgM-monoclonal gammopathy have been reported." (PMID 30992531, 2019). "In clinically indistinguishable anti-MAG neuropathy without seropositivity of MAG and SGPG, the IgM may react to gangliosides such as GD1b, GT1b, and GQ1b." (PMID 30941082, 2019). "However, we enrolled only one patient with anti-MAG neuropathy, and we could not provide reliable data on the effectiveness of TPE in this case." (PMID 39051217, 2024). "We will consider the treatment separately for idiopathic DADS (DADS-I), DADS with monoclonal paraproteinemia without anti-MAG antibody (DADS-M) and anti-MAG neuropathy, with or without DADS phenotype." (PMID 33790853, 2021).
monoclonal gammopathy (34 papers, 2013 to 2025). A condition characterized by the abnormal presence of monoclonal immunoglobulins in the blood or urine. "Anti-MAG polyneuropathy is the most common paraproteinemic IgM neuropathy frequently associated with an IgM monoclonal gammopathy of undetermined significance (MGUS); however, it can be also related to a lymphoproliferative condition." (PMID 41031196, 2025). "Nutritional neuropathies, often associated with vitamin deficiencies, and immune-mediated forms such as polyneuropathy associated with monoclonal gammopathy or anti-MAG antibody neuropathy—commonly found in lymphoproliferative disorders—were also included." (PMID 41303084, 2025). "The association of IgM monoclonal gammopathy with demyelinating neuropathy and anti-MAG antibodies was first reported by Latov and colleagues in 1980,1, 2, 3and subsequently confirmed by other investigators." (PMID 38325389, 2024). "In anti-MAG antibody neuropathy, the paraprotein is associated with monoclonal gammopathy of undetermined significance (MGUS) in approximately 80% of patients, and with Waldenström macroglobulinemia (WM) in the remaining 20%." (PMID 33498362, 2021). "Although the association of IgM monoclonal gammopathy and anti-MAG antibodies is very strong, these recommendations likely generate a selection bias." (PMID 30992531, 2019). "This happens with other nerve antigens such as myelin-associated glycoprotein in polyneuropathy associated with monoclonal gammopathy or NF155 and should be taken into account in future studies." (PMID 29089585, 2017). "Other ancillary tests confirmed the IgM monoclonal gammopathy (7.3 g/L; N < 1.7) with a Kappa light chain (52.5 mg/L; N < 19.4) and a high level of antimyelin-associated glycoprotein (MAG) antibodies (>70,000 Bühlmann Titer Unit)." (PMID 25621682, 2015). "Polyneuropathy associated with IgM monoclonal gammopathy and anti-myelin associated glycoprotein (MAG) antibodies is an immune-mediated demyelinating neuropathy." (PMID 26065001, 2015). "We have described a series of patients with polyneuropathy associated with IgM monoclonal gammopathy and anti-MAG antibodies." (PMID 26065001, 2015). "Furthermore, an immunoglobulin M (IgM) monoclonal gammopathy is nearly always present, and anti-MAG antibodies − considered the diagnostic hallmark − are invariably detectable [33▪▪]." (PMID 40748018, 2025). "On the other hand, IL-10 production was associated with disease development in several animal models of CIDP, as well as with a CIDP variant with anti-neurofascin 155 antibodies and polyneuropathy associated with IgM monoclonal gammopathy with anti-MAG antibodies." (PMID 37626843, 2023). "Increased IGHV3-23 usage is also reported in anti-myelin associated glycoprotein neuropathy and in monoclonal gammopathy of undetermined significance, a disorder that may progress to malignant lymphoproliferative disease." (PMID 32692761, 2020). "In addition, two-thirds of patients with DADS have IgM monoclonal gammopathy, and the disease is usually associated with anti-MAG antibodies." (PMID 25105500, 2014). "According to EAN/PNS 2021 recommendations for CIDP, anti-MAG-ab should also be tested in all patients fulfilling CIDP diagnostic criteria and in presence of IgM monoclonal gammopathy." (PMID 39555481, 2024). "This complexity also underscores the necessity to consider anti-MAG antibodies and monoclonal gammopathy in patients who present with demyelinating peripheral neuropathy." (PMID 38912071, 2024). "The anti-MAG is characteristic of IgM monoclonal gammopathy of uncertain significance polyneuropathy, which shows over 50% seropositivity; however, anti-MAG appears in 5.6% of patients without monoclonal gammopathy." (PMID 37046492, 2023). "All eight patients diagnosed with IgM monoclonal gammopathy and the patient with IgG-IgM biclonal gammopathy had anti-MAG antibodies present in the serum." (PMID 35885595, 2022).
monoclonal gammopathy (continued). "Anti-MAG antibody titers and presence of IgM monoclonal gammopathy by immunofixation was tested periodically in these patients depending on their visit schedules." (PMID 30992531, 2019). "In patient 1, the detection of monoclonal gammopathy coincided with a significant increase in anti-MAG antibody titers." (PMID 30992531, 2019). "Either early testing of anti-MAG or repeated testing of monoclonal gammopathy by immunofixation have to be considered then, especially in patients with clinical and electrophysiological features resembling typical anti-MAG+ MGUSP." (PMID 30992531, 2019). "In two of them, IgM-monoclonal gammopathy was detected at 3 and 4-year follow-up coinciding with an increase in anti-MAG antibodies titers." (PMID 30992531, 2019). "In two of our patients an IgM monoclonal gammopathy was detected by serum immunofixation years after diagnosis, and in patient 1 it clearly coincided with an increase in anti-MAG titers." (PMID 30992531, 2019). "Western blot (WB) analysis has long been the gold standard for detection of anti-MAG antibodies and positive WB is present in approximately 50% of patients with IgM monoclonal gammopathy and a demyelinating polyneuropathy." (PMID 26065001, 2015). "Since anti-MAG antibodies are found in more than 70% of patients with typical M component-related demyelinating polyneuropathy, in clinical practice, an anti-MAG antibody test is performed only in patients with detectable IgM monoclonal gammopathy." (PMID 36672019, 2022). "However, the IgM monoclonal gammopathy group and the IgG-IgM biclonal gammopathy case, which all had in common serum anti-MAG activity, demonstrated a widening of the outermost myelin lamellae." (PMID 35885595, 2022). "MAG is considered to be the antigenic target of IgM–anti-MAG peripheral neuropathy associated with monoclonal gammopathy, but it has not been verified in animal experiments." (PMID 34975399, 2021). "Here we investigate the presence of anti-MAG antibodies in patients fulfilling diagnostic criteria for chronic inflammatory demyelinating polyradiculoneuropathy (CIDP) without IgM monoclonal gammopathy." (PMID 30992531, 2019). "Moreover, due to the association of anti-MAG antibodies to the presence of MGUS, all four patients underwent hematological follow-up to study the appearance of monoclonal gammopathy." (PMID 30992531, 2019). "All patients had IgM monoclonal gammopathy and anti-MAG antibodies." (PMID 26065001, 2015). "Indeed, it has long been demonstrated that MAG behaves as a self-antigen in patients with polyneuropathy and IgM monoclonal gammopathy." (PMID 26065001, 2015). "Nonetheless, anti-MAG titers may serve as an indirect marker of therapeutic response, particularly in the context of B-cell depleting therapies such as RTX, as they likely reflect suppression of the underlying monoclonal gammopathy." (PMID 41031196, 2025). "Anti-MAG IgM antibodies should be tested in any patients with a predominantly distal demyelinating neuropathy (DADS phenotype) and in the presence of IgM monoclonal gammopathy." (PMID 39555481, 2024). "EAN/PNS guidelines suggest searching for monoclonal gammopathy in all patients with suspected CIDP, and if an IgM paraprotein is present, anti-MAG antibodies must be tested." (PMID 36672019, 2022). "Although these reports are anecdotical, it is suggested to test anti-MAG antibodies in patients with distal chronic sensorimotor demyelinating neuropathy, regardless of the detection of IgM monoclonal gammopathy." (PMID 36672019, 2022). "In conclusion, anti-MAG antibody testing should be considered in chronic demyelinating neuropathies, even if IgM-monoclonal gammopathy is not detectable." (PMID 30992531, 2019). "Monoclonal gammopathy of neurologic significance (MGNS) may be diagnosed if the following factors are present: symmetric sensory deficits, slow progression, length dependence, strongly positive anti-MAG antibodies, and prominent demyelination on EMG." (PMID 36591532, 2022).
monoclonal gammopathy (continued). "An anti-MAG antibody should be tested, regardless of the detection of IgM monoclonal gammopathy, in patients complaining distal sensory symptoms, mild weakness, sensory ataxia, and hand tremor that show at NCS a demyelinating neuropathy more pronounced in distal segments (abnormal prolonged DML)." (PMID 36672019, 2022). "Our observations suggest that there is a subset of patients with anti-MAG + polyneuropathy without any detectable monoclonal gammopathy that may remain undiagnosed." (PMID 30992531, 2019). "We identified four (5.8%) anti-MAG positive patients without detectable IgM-monoclonal gammopathy." (PMID 30992531, 2019). "The two CIDP patients with IgM monoclonal gammopathy were anti-MAG negative." (PMID 30992531, 2019). "Anti-MAG antibodies were detected in four patients (6.9% of the seronegative patients; 5.8% of the whole CIDP cohort) without IgM monoclonal gammopathy." (PMID 30992531, 2019).